ALB (albumin)
Diseases named in the same sentence as ALB in open-access papers (continued):
Sharing a sentence is not in itself a finding about the gene and the disease.
liver failure (continued). "Intrasplenic or injection of SC-derived hepatocytes to human or animal with liver injury or liver failure increased ALB, AFP, CK-19, and antitripcin mRNA expression, ALB secretion, serum ALB concentration, and reduced bilirubinemia." (PMID 36685673, 2023). "In the present work, there was an important elevate in serum rates of ALP, ALT, and AST, along with a subsequent decrease in albumin and total protein levels in ESC-bearing mice, demonstrating liver failure." (PMID 35844382, 2022). "The total bilirubin (TBIL), direct bilirubin (DBIL), cholinesterase (CHE), serum albumin (ALB), prothrombin time (PT) and international normalized ratio (INR) should be assessed in liver failure or decompensated cirrhosis." (PMID 35273978, 2022). "The results revealed fourteen independent risk factors including; age, temperature, heart rate, respiratory rate, MAP, SpO2, mechanical ventilation, albumin, bilirubin, lactate, BUN, AIDS, hepatic failure and metastatic cancer." (PMID 34325720, 2021). "Patients presenting with liver failure were screened for eligibility and after inclusion were randomly assigned to be started on either conventional MARS or SPAD (with 4 % albumin and a dialysis flow rate of 700 ml/h)." (PMID 26728364, 2016). "Upon transplantation of clonal lines to a Fah−/−Il2rg−/− rat model of liver failure, the rat liver stem cells engrafted into the host liver where they differentiated into areas with FAH and Albumin positive hepatocytes." (PMID 26915950, 2016). "There were strong positive relation between Af-Gc levels and ALB, CHE, ALT, AST (P = 0.001, < 0.001, < 0.001, < 0.001, respectively); Af-Gc globulin was correlated with Child-Pugh score in liver failure patients (r = – 0.313, P = 0.02)." (PMID 27942277, 2009). "Patients who undergo PA-TACE prematurely are prone to liver failure and other serious complications, as their liver function has not fully recovered, their albumin level is low, and infection has not been completely controlled." (PMID 36969018, 2023). "Systemic edema, hepatic failure, and inflammation all have a negative influence on serum albumin levels." (PMID 36562034, 2022). "On the other hand, both DBP and albumin levels in liver failure patients are lower than those in normal subjects; however, total 25(OH)D levels are also low in patients with liver failure." (PMID 36107130, 2022). "Multivariable logistic regression analysis identified age ≥ 50 years, temperature < 37 °C, respiratory rate > 35 breaths/min, MAP ≤ 50 mmHg, SpO2 < 90%, albumin ≤ 2 g/dL, bilirubin ≥ 0.8 mg/dL, lactate ≥ 4.2 mmol/L, BUN ≥ 21 mg/dL, mechanical ventilation, hepatic failure and metastatic cancer." (PMID 34325720, 2021). "Children with acute liver failure significantly had more prolonged PT and aPPT, and higher INR values in coagulation assays; and had higher levels of albumin in biochemical tests than the group without liver failure (for all, p ≤ 0.05)." (PMID 34461848, 2021). "The expired neonate had no sign of liver failure (Hepatomegaly, raising of liver function test or decrease of albumin level." (PMID 33596978, 2021). "We found identical levels of albumin in Epac1−/− and WT mice, suggesting that the decreased coagulation factor levels in Epac1−/− mice are not a result of liver failure." (PMID 28821815, 2017). "Although hepatic impairment is known to decrease albumin production, only 12.5% of patients in the present study showed hepatotoxicity at the time of development of myelosuppression, and none developed liver failure." (PMID 27128679, 2016). "According to the toxin hypothesis of liver failure, extracorporeal albumin dialysis (ECAD) may provide a therapeutic option during critical care by reducing endogenous albumin-bound toxic agents such as bile acids." (PMID 26728364, 2016).
liver failure (continued). "In none of the patients, the combination of AST and/or ALT above upper limit of normal (ULN), bilirubin above ULN and albumin below lower limit of normal was found, and therefore it was concluded that none of the patients had liver failure." (PMID 26762381, 2016). "Whereas elimination of albumin-bound substances such as bilirubin or bile acids has been well defined for both MARS and Prometheus, little is known of their impact on pathophysiology of liver failure." (PMID 17156425, 2006). "The fact that prothrombin time, INR, albumin, or the development of hepatic insufficiency events such as encephalopathy are not included in the CTCAE criteria could merit discussion, but this is not the purpose of the present review." (PMID 36140517, 2022). "A major limitation of prognostic scores in AVB is the fact that classical prognostic scores reflect only bleeding severity (excluding albumin level in AIMS65), whereas liver failure scores (CTP and MELD) are not correlated with bleeding severity." (PMID 40863238, 2025). "None of patients with INCPH had signs of liver failure defined as INR > 1.5 and albumin < 3.5 and none bled from varices." (PMID 24741616, 2014). "Albumin levels were significantly lower in MAFLD patients compared to non-MAFLD patients, suggesting an early decline in liver synthetic function despite the absence of overt liver failure." (PMID 40954485, 2025). "First, as can be seen in the formula used to obtain free 25(OH)D [free 25(OH)D = total 25(OH)D/(1+(6 × 105 × albumin) + (7 × 108 × DBP))], the calculated free 25(OH)D levels could be lower in PRG subjects than in NOR subjects and patients with liver failure." (PMID 36107130, 2022). "Hepatocyte markers ALB, TTR and alcohol dehydrogenase 1A (ADH1A) were not significantly DE between normal and early ALD but were significantly downregulated in AH versus early ALD, suggesting a secondary transcriptomic response following onset of liver failure." (PMID 40122595, 2025).
colorectal cancer (194 papers, 1974 to 2026). A primary or metastatic malignant neoplasm that affects the colon or rectum. "Studies have shown that the pan-immune inflammation value and albumin-to-globulin ratio are closely associated with the tumor immune microenvironment and serve as important prognostic indicators in colorectal cancer." (PMID 41048937, 2025). "The most important independent risk factors associated with AL among patients with colorectal cancer were pre-operative such as lower preoperative serum albumin levels, followed by a higher ASA Score, clinical-stage III-IV, and an age ≥65 years old." (PMID 38774568, 2024). "Specifically, the preoperative C-reactive protein/albumin ratio was independently associated with long-term prognosis in patients aged ≥ 70 years with stage I-III colorectal cancer after curative resection." (PMID 38280961, 2024). "In a study involving colorectal cancer patients, an increase of 0.1 g/dL in albumin levels was associated with a 7.3% decrease in morbidity and a 15.6% decrease in mortality." (PMID 38500655, 2024). "One study examined the association between circulating liver function markers including albumin and colorectal cancer (CRC) risk in a large prospective cohort of 375,693 UK Biobank participants." (PMID 37836494, 2023). "ALB has been identified as one of the liver metastasis-associated hub genes in colorectal carcinoma." (PMID 37887568, 2023). "Nutritional and immune biomarkers in the peripheral blood, including albumin, globulin, lymphocytes, and neutrophils, are associated with the prognosis of colorectal cancer." (PMID 35909159, 2022). "And low levels of serum albumin are associated with a poor overall prognosis in patients with colorectal cancer." (PMID 34150609, 2021). "For colorectal cancer, we observed an inverse association between pre‐diagnostic albumin levels and colorectal cancer risk, which was consistent with the results of several previous studies." (PMID 34041866, 2021). "Ishioka found that the factors associated with a poorer prognosis included colorectal cancer, three or more events related to metastatic disease, degree of hydronephrosis, and serum albumin <3 g/dL." (PMID 34072127, 2021). "The aim of this study was to examine the relationship between albumin, nutritional risk, body composition, systemic inflammation, and outcomes in patients with colorectal cancer (CRC)." (PMID 32708140, 2020). "The change in the level of acute-phase reactants, such as CRP, ferritin, fibrinogen, D-dimer, haptoglobin, and albumin, was found to be associated with a dismal prognosis and survival outcome in colorectal cancer patients in various settings of the disease." (PMID 29949857, 2018). "It should allow a comprehensive and systematic screening for undernutrition in elderly patients hospitalized for colorectal cancer based on the knowledge of patient weight loss, body mass index, albumin concentration and MNA." (PMID 28061830, 2017). "A low serum albumin level before surgery is known to be associated with poor outcomes in patients with colorectal cancer." (PMID 28836976, 2017). "For gastrointestinal cancer, higher risks of oesophageal and colorectal cancer were linked to higher levels of albumin-corrected calcium in women, indicating the importance of calcium correction based on albumin levels." (PMID 26284119, 2015). "We analyzed this database with respect to the exact nutritional state of colorectal cancer patients and compared these data to patients with other common cancers using albumin level, body weight loss and BMI." (PMID 26345703, 2015). "Similarly, in colorectal cancer surgery, low preoperative serum albumin levels were associated with an increased risk of surgical complications such as surgical site infections and prolonged hospital stays (OR 1.79, p<0.05)." (PMID 40161084, 2025). "Association between serum albumin, uric acid, neutrophils and colorectal cancer." (PMID 38745951, 2024).
colorectal cancer (continued). "A decrease in pre-operative albumin might be associated with inflammation which increases tissue catabolism, and patients with colorectal cancer might have accelerated loss of albumin from the gastrointestinal tract." (PMID 36105581, 2022). "Moreover, a meta-analysis further evidenced that serum albumin was an independent risk factor for POD in colorectal cancer surgery." (PMID 36062155, 2022). "In addition, high neutrophil to lymphocyte ratios and low albumin levels were correlated with muscle loss and myosteatosis in colorectal cancer patients and an association with systemic inflammatory response highlighted." (PMID 31717736, 2019). "In addition to NLR, other markers of systemic inflammatory response, such as CRP and mGPS (CRP and albumin), have been shown to be risk factors for inferior survival in colorectal cancer." (PMID 25406793, 2014). "Using albumin-corrected calcium, we found a positive link with with colon as well as colorectal cancer risk in women [e.g. HR for colon and colorectal cancer: 1.07 (95% CI: 1.02-1.13) and 1.06 (95% CI: 1.02-1.11) for every SD increase in corrected calcium, respectively]." (PMID 23866097, 2013). "The fibrinogen-to-albumin ratio (FAR) has been extensively studied for its potential to predict the prognosis of patients with colorectal cancer (CRC)." (PMID 40650392, 2025). "As early as 1978, research teams began exploring the significance of prealbumin, retinol-binding protein, transferrin, and albumin levels in colorectal cancer patients." (PMID 41450918, 2025). "Pre-treatment ALP elevation was associated with poor survival, low albumin levels, and serum carcinoembryonic antigen (CEA) elevation in colorectal cancer patients." (PMID 39941572, 2025). "Albumin (ALB) and total protein (TP) are vital constituents of the blood, and their levels and roles in the risk of colorectal cancer (CRC) are of significance." (PMID 41189249, 2025). "NPS, a system evaluating prognosis with factors like albumin, cholesterol, and inflammatory cell ratio, was developed from a colorectal cancer study." (PMID 40357040, 2025). "In this context, the aim of this work was to develop and evaluate DEX-coated albumin nanoparticles as carriers for bevacizumab in a colorectal cancer mice model." (PMID 39455507, 2024). "Colorectal cancer patients with albumin levels above 3.5 g/dL had a significantly higher 5-year survival rate compared to those with levels below 3.5 g/dL (66% vs 34%, P < 0.001)." (PMID 38500655, 2024). "In research of 431 patients with curative colorectal cancer, serum albumin level was identified as a reliable prognostic marker for survival." (PMID 39440062, 2024). "The results revealed that PNI, albumin levels, ASA, and tumor diameter emerged as independent risk factors for recent complications after colorectal cancer surgery." (PMID 39568563, 2024). "PNI ≥45, Albumin <40 g/L, ASA score III-IV, and Tumor diameter ≥5 cm emerged as independent risk factors for recent complications following colorectal cancer surgery." (PMID 39568563, 2024). "In the present study, a significant increase in blood albumin levels among the participants of combined ω3+VitD supplements over 9 weeks is in accordance with the observation of a clinical trial study of 81 colorectal cancer patients." (PMID 39599746, 2024). "Pre-treatment serum albumin concentration has been used as a prognostic indicator for various neoplastic diseases such as non-small cell lung cancer, colorectal carcinoma, acute amyloid leukemia, and lymphoma in humans." (PMID 38595652, 2024). "where the deterioration of colorectal cancer can be prevented with a healthy diet by controlling glucose hemostasis to maintain the patient’s energy balance as well as increase body weight, albumin and prealbumin." (PMID 38113874, 2023). "The preoperative albumin values of gastric and colorectal cancer were 38.2 ± 4.4 g/l and 38.7 ± 2.8 g/l (p = 0.46), respectively." (PMID 36814253, 2023).
colorectal cancer (continued). "CA, through its inhibitory effects on cell growth, migration, and induction of apoptosis, proves effective against colorectal cancer, particularly when delivered via bovine serum albumin (BSA) nanoparticles." (PMID 38202397, 2023). "Preoperative serum albumin is well-known as an effective predictor of the outcome of colorectal cancer surgery and a component of nutritional screenings, such as the Prognostic Nutritional Index and Nutritional Risk Index." (PMID 37260520, 2023). "The albumin values of gastric and colorectal cancer before the discharge were 32.6 ± 3.8 g/l and 32.5 ± 3.6 g/l (p = 0.92), respectively." (PMID 36814253, 2023). "It has been reported that Osaka prognostic score (OPS), based on C-reactive protein (CRP), total lymphocyte counts (TLC) and albumin (ALB), was relevant to prognosis in colorectal cancer." (PMID 35300627, 2022). "Another example of combined therapy with albumin-based nanoparticles in colorectal cancer is the 131I-antiEGFR–BSA–PCL system based on bovine serum nanoparticles (BSA)." (PMID 35631681, 2022). "In a second study of persons with colorectal cancer receiving oxaliplatin, albumin levels were lower in the group that developed grade 2–3 neuropathy, compared to those that developed grade 0–1 (3.9 ± 0.3 vs. 4.1 ± 0.4, p = 0.001)." (PMID 35054049, 2022). "In this study, we developed a novel indicator—LANR, which was based on lymphocytes, neutrophils, and albumin, and the results showed that the indicator was significantly correlated with the prognosis of colorectal cancer patients." (PMID 34150609, 2021). "Several studies have demonstrated that pretreatment ALB is a prognostic factor in various cancers, including lung, pancreatic, gastric, and colorectal cancers." (PMID 34692474, 2021). "First, studies have found that the ratio of serum bilirubin to albumin is an important prognostic factor for patients with colorectal cancer with liver metastasis." (PMID 33478423, 2021). "Serum albumin can accurately reflect both nutritional and inflammatory status and is independently correlated with survival in patients with colorectal cancer." (PMID 34708064, 2021). "The prognostic impact of the combination of the modified Glasgow prognostic score (mGPS) and C-reactive protein/albumin ratio (CAR) in colorectal cancer (CRC) is unclear." (PMID 33105743, 2020). "BMI and serum albumin levels are the most commonly used indicators for assessing nutritional status, and are useful indicators for assessing the prognosis of colorectal cancer." (PMID 33083140, 2020). "Another prognostic score simultaneously considering NLR, the lymphocyte-to-monocyte ratio, albumin, and cholesterol is a simple and effective tool for predicting survival in patients with colorectal cancers." (PMID 31737102, 2019). "Third, some studies have found the prognostic value of the ratio CRP/Albumin in tumours, such as oesophageal squamous cell cancer, ovarian cancer, and colorectal cancer." (PMID 31781301, 2019). "We aimed to assess the usefulness of preoperative plasma albumin concentration and their changes as indicators of infectious complications in patients undergoing colorectal cancer surgery." (PMID 29340818, 2018). "A previous study has revealed that the albumin/globulin ratio (GAR) before treatment is a predictor of cancer‐specific survival in patients with colorectal cancer (CRC)." (PMID 30460347, 2018). "The aim of this study was to evaluate the usefulness of albumin level measurements as an early predictor of infectious complications in patients with colorectal cancer undergoing laparoscopic surgery with ERAS protocol." (PMID 29340818, 2018). "It has been revealed that AOPPs, the dityrosine containing protein cross-linking products formed by the attack of ROS on albumin and are increased significantly in colorectal carcinoma, similar findings were seen in this study." (PMID 29930913, 2018).